KCNQ3 (potassium voltage-gated channel subfamily Q member 3)
Diseases named in the same sentence as KCNQ3 in open-access papers (continued):
Sharing a sentence is not in itself a finding about the gene and the disease.
autism spectrum disorder (6 papers, 2013 to 2026). A spectrum of developmental disorders that includes autism, and Asperger syndrome. "For example, although multiple groups have identified orthologous Kcnq3 gain of function variants in patients with autism spectrum disorders or electrical status epilepticus in sleep, these patients do not show evidence of disordered breathing." (PMID 38052789, 2023). "An additional possible example is provided by another neuronal paralog, KCNQ3, for which the corresponding R230C mutation was recently identified as a genetic risk factor for autism spectrum disorder." (PMID 33600800, 2021). "Interestingly, mutations found in cluster 3.1 in KCNQ3 S4 (R227Q, R230C, and R236C) are known GoF gating mutations implicated in autism spectrum disorders, indicating that cancers are selecting for mutations that increase KCNQ3 channel gating activity." (PMID 37748809, 2023).
developmental delay (6 papers, 2019 to 2024). "In contrast, KCNQ3 variants have been identified in patients with developmental delay and neonatal seizures, suggesting that KCNQ3 variants are compatible with life." (PMID 39434833, 2024). "This is the first study exploring the functional consequences of a novel KCNQ3 homozygous LoF variant responsible for a severe phenotype characterized by neonatal‐onset pharmacodependent seizures, with developmental delay and ID." (PMID 31440727, 2019).
Anxiety (5 papers, 2013 to 2025). Intense feelings of nervousness, tension, or panic often arise in response to interpersonal stresses. "This suggests that the male Kcnq3-W266L mice have a lower level of certain anxiety elements compared to the wild-type mice." (PMID 37305551, 2023). "However, the male Kcnq3-W266L mice spent a significantly longer time in the open arms, indicating a lower level of anxiety in these mice, while the female Kcnq3-W266L mice spent the same amount of time in the open arms as the wild-type mice." (PMID 37305551, 2023).
Benign familial neonatal seizures (5 papers, 2020 to 2023). Benign familial neonatal seizures (BFNS) is a rare epilepsy of the newborn characterized by partial or generalized seizures, which occur during wakefulness and/or sleep. "For e.g. variations in KCNQ2 and KCNQ3 having 85% penetrance are identified as causal factor of benign familial neonatal seizures." (PMID 33096746, 2020). "The members of the KCNQ family, especially KCNQ2 and KCNQ3, encode voltage-gated potassium channels (VGKC), which are associated with epilepsy, such as benign familial neonatal seizures (BFNS)." (PMID 36835631, 2023). "KCNQ3 c.1226C>G was reported as VUS in benign familial neonatal seizures." (PMID 35806193, 2022). "Benign familial neonatal seizures (BFNS) as another early-onset epilepsy have been revealed to be associated with loss-of-function mutations of voltage-gated potassium channel genes, including KCNQ2 (potassium voltage-gated channel subfamily Q member 2) and KCNQ3." (PMID 36835631, 2023). "Two KCNQ3 variants have been reported in ClinVar; c.1885G>A was reported two times, once as a VUS in benign familial neonatal seizures and as once as likely benign without linking to a specific phenotype, while the c.1706A>G variant was reported as a VUS, and the phenotype was not provided." (PMID 36430572, 2022).
bipolar disorder (5 papers, 2013 to 2025). A disorder of the brain that causes unusual shifts in mood, energy, activity levels and the ability to carry out day-to-day tasks. "KCNQ3, coding for a voltage-gated potassium channel, is specifically down-regulated in microglia, suggesting a role in the excitation-inhibition imbalance and neuronal hyperexcitability implicated in bipolar disorder and schizophrenia." (PMID 40053590, 2025). "The 6q14 locus, which was repeatedly shown to contain alleles increasing susceptibility to ADHD, schizophrenia, and bipolar disorder, was also shown to contain loss of function allele of KCNQ3 in affected family members with Benign Familial Neonatal Convulsions." (PMID 32120974, 2020). "Electrical excitation of neurons is facilitated by KCNQ3, and disruption of this protein is associated with neurological conditions, such as benign familial newborn convulsions, and psychiatric conditions, such as bipolar disorder and attention deficit hyperactivity disorder." (PMID 39838666, 2025).
Encephalopathy (4 papers, 2021 to 2024). Encephalopathy is a term that means brain disease, damage, or malfunction. "In the present study, we evaluated the therapeutic potential of donepezil, a reversible acetylcholinesterase inhibitor approved by the FDA, in four children affected by GoF variants of KCNQ2 and KCNQ3 encephalopathy." (PMID 39175503, 2024). "Donepezil should be repurposed as a novel alternative treatment for GoF variants in KCNQ2/KCNQ3 encephalopathy." (PMID 39175503, 2024). "KCNQ2 and KCNQ3 variants can also lead to severe refractory epilepsy accompanied by encephalopathy and cognitive decline." (PMID 38003469, 2023). "Although the most frequent KCNQ2 and KCNQ3 mutations are LoF, some KCNQ2 variants causing encephalopathy may present GoF characteristics, with increased channel activity, altered kinetics, and more severe clinical manifestation in affected patients." (PMID 38003469, 2023). "Moreover, most patients with KCNQ2 encephalopathy carry a heterozygous mutation; thus, the pharmacological responses in the condition when mutation co-expressed with KCNQ2 WT and KCNQ3 (1:1:2 ratio) may better represent the therapy response." (PMID 36932231, 2023). "Not surprisingly, patients with encephalopathy resulting from GoF KCNQ3 variations do not benefit from treatment with sodium channel blockers, while retigabine can even aggravate encephalopathy symptoms." (PMID 38003469, 2023).
hearing loss (4 papers, 2014 to 2023). "Therefore, we tested the effects of ICA-105665, a novel small molecule that selectively opens KCNQ2/3 and KCNQ3/5 channels (Kv7.2/7.3 and Kv7.3/7.5) to determine its effects on salicylate-induced hearing loss." (PMID 25904892, 2015). "However, the function of KCNQ2/3 and KCNQ3/5 in salicylate-induced cochlear hearing loss is poorly understood." (PMID 25904892, 2015). "For example, dimers of KCNQ3/4 modulate the dynamics of activation of hearing loss-associated candidate KCNQ4 and might contribute to the critical low-voltage activated potassium conductance in both inner and outer hair cells of mice." (PMID 26121033, 2015). "In this study, we tested whether opening voltage-gated potassium channels using ICA-105665, a novel small molecule that opens KCNQ2/3 and KCNQ3/5 channels, can reduce salicylate-induced hearing loss." (PMID 25904892, 2015).
Tinnitus (4 papers, 2014 to 2024). Tinnitus is an auditory perception that can be described as the experience of sound, in the ear or in the head, in the absence of external acoustic stimulation. "Dysfunction of KCNQ2 and KCNQ3 channels—voltage-dependent potassium ion channels—in the cochlear nucleus can cause tinnitus." (PMID 39296986, 2024). "Moreover, dysfunction of KCNQ2 and KCNQ3 channels in the cochlear nucleus can cause tinnitus." (PMID 39296986, 2024). "This study aimed to elucidate the pathological roles of KCNQ2 and KCNQ3 channels within the auditory cortex in tinnitus development and examine the therapeutic potential of mid-infrared photons for tinnitus treatment." (PMID 39296986, 2024). "Despite the recognized significance of KCNQ2 and KCNQ3 channels in the auditory cortex, their precise relationship and implications in the pathogenesis of tinnitus remain areas of scientific inquiry." (PMID 39296986, 2024). "In this study, we explored the pathological roles of KCNQ2 and KCNQ3 channels in the auditory cortex in tinnitus development, emphasizing the crucial role of hyperexcitability of excitatory neurons." (PMID 39296986, 2024). "In this study, we observed decreased latency of APs in pyramidal neurons in tinnitus animals, indicating KCNQ2 and KCNQ3 channel dysfunction." (PMID 39296986, 2024). "Considering the strong correlation between AP latency and KCNQ2 and KCNQ3 channels, the observed shorter latency in the tinnitus group may be attributed to abnormal functioning or expression of KCNQ2 and KCNQ3 channels." (PMID 39296986, 2024). "For example, there was a trend toward greater staining for KCNQ3, NLRP3, and CD68 and lower staining for PREX2 and APLN in the VS samples associated with tinnitus compared to those without tinnitus." (PMID 37048724, 2023). "However, the precise correlation between KCNQ2 and KCNQ3 channels within the auditory cortex and the etiology of tinnitus have not yet been fully elucidated." (PMID 39296986, 2024).
Ataxia (3 papers, 2015 to 2022). Ataxia refers to impaired coordination of voluntary muscle movement. "For instance, the mutated KCNQ2 and KCNQ3 genes, which encode Kv7.2 and Kv7.3, respectively, enable benign familial neonatal convulsions, and genetic suppression of small-conductance Ca2+-activated K+ channels (SK) in deep cerebellar neurons can result in ataxia." (PMID 36393851, 2022).
schizophrenia (3 papers, 2009 to 2025). A major psychotic disorder characterized by abnormalities in the perception or expression of reality. "They found that wild type PIP5K2A, but not the schizophrenia-associated mutant (N251S)-PIP5K2A, was able to activate the heteromeric KCNQ2/KCNQ3 and KCNQ3/KCNQ5 channel complexes that make up the neuronal voltage-gated potassium M channels." (PMID 19445674, 2009).
convulsion (2 papers, 2019 to 2020). A rapid and repeated body muscle contract that results in an uncontrolled shaking of the body. "Mutations in two family members, Potassium Voltage-Gated Channel Subfamily Q Member 2 (KCNQ2) and Potassium Voltage-Gated Channel Subfamily Q Member 3 (KCNQ3), have been correlated with inherited neonatal epilepsy, e.g., benign family neonatal convulsions." (PMID 31151179, 2019).
idiopathic generalized epilepsy (2 papers, 2010 to 2013). A generalised epilepsy that encompasses several common seizure phenotypes including childhood absence epilepsy, juvenile absence epilepsy, juvenile myoclonic epilepsy and epilepsy with generalized tonic-clonic seizures alone. "Heterozygous mutations in the KCNQ3 gene on chromosome 8q24 encoding the voltage-gated potassium channel KV7.3 subunit have previously been associated with rolandic epilepsy and idiopathic generalized epilepsy (IGE) including benign neonatal convulsions." (PMID 23596459, 2013). "Mutations in the genes KCNQ2 and KCNQ3 cause idiopathic generalized epilepsy (IGE)." (PMID 23596459, 2013). "The molecular identity that underlies the M-current was discovered as a result of identification of mutations in human potassium channel subunits referred to as KCNQ2 (Kv7.2) and KCNQ3 (Kv7.3) from idiopathic generalized epilepsy patients." (PMID 20796319, 2010).
mood disorder (2 papers, 2013 to 2020). A cognitive disorder a disturbance in which the person's mood is hypothesized to be the main underlying feature. "Early pharmacological evidence suggests a potential mechanistic role of KCNQ3 regulators in mood disorders." (PMID 32120974, 2020). "Here, we report a reduction trend of KCNQ3 levels in the DLPFC of male suicide victims with mood disorders." (PMID 32120974, 2020).
Rolandic epilepsy (2 papers, 2013 to 2015). "KCNQ3 and KCNQ2 gene mutations segregate with various forms of Kv7.3/Kv7.2-channelepsies such as benign familial neonatal convulsion (BFNC) and rolandic epilepsy." (PMID 25784856, 2015).
benign adenoma (1 paper, 2023). "In benign adenoma tissue, there are an up-regulation of KCNQ3 and a slight decrease in KCNQ1." (PMID 37748809, 2023).
benign neonatal epilepsy (1 paper, 2015). "– G311V pore mutation: benign neonatal epilepsy.– De novo interstitial deletion in the long arm of chromosome 8 encompassing KCNQ3: psychomotor delay and convulsions." (PMID 25784856, 2015).
Dravet syndrome (1 paper, 2023). "For example, mutations in the SCN1A gene are associated with Dravet syndrome, while mutations in the KCNQ2 and KCNQ3 genes are linked to benign familial neonatal epilepsy (BFNE)." (PMID 37927689, 2023). "For example, SCN1A mutations are linked to Dravet syndrome, while mutations in KCNQ2 and KCNQ3 are associated with benign familial neonatal epilepsy." (PMID 37927689, 2023).
early-onset epilepsy (1 paper, 2026). "While previous reports primarily associate KCNQ3 mutations with early-onset epilepsy, this case suggests a broader neurodevelopmental impact, including ASD traits and neuroimaging abnormalities, emphasizing the importance of genetic screening in complex epilepsy syndromes." (PMID 42255468, 2026).
neuroblastoma (1 paper, 2024). Neuroblastoma (NB) is the most common solid, extracranial childhood tumor. "KCNQ3 plays a similar role as the GABAA receptor in neurotransmission during early development, emphasising the key role of neurodevelopmental genes and suggesting an association with neuroblastoma." (PMID 38398114, 2024).
oesophageal adenocarcinoma (1 paper, 2023). "We chose to reduce the expression of KCNQ1 using a CRISPR/Cas9-induced knockout (KO) and overexpression (OE) KCNQ3 in oesophageal adenocarcinoma cell lines OE33 and FLO-1." (PMID 37748809, 2023). "We combined patient data from The Cancer Genome Atlas (TCGA) with our own oesophageal adenocarcinoma data (OCCAMS) as part of the International Cancer Genome Consortium, in which KCNQ3 is recurrently missense mutated in 9.4% of patients." (PMID 37748809, 2023). "We compared GO biological process terms associated with significantly differentially expressed genes (Q < 0.05) for OE33 KCNQ3 OE versus WT, and for the 25 highest and lowest KCNQ3-expressing patients with oesophageal adenocarcinoma." (PMID 37748809, 2023). "KCNQ1 plays a role in colon cancer and in hepatocellular carcinoma, and KCNQ3 is hypermutated in oesophageal adenocarcinoma." (PMID 37748809, 2023).
oesophageal cancer (1 paper, 2023). "Through integration of data at the patient, cell, and protein structural levels, coupled with in vitro models, we show that KCNQ genes, specifically KCNQ1 and KCNQ3, and their protein products contribute to gastro-oesophageal cancer phenotype and are a potential therapeutic target." (PMID 37748809, 2023).
preeclampsia (1 paper, 2018). Preeclampsia is a hypertensive disorder of pregnancy that is characterized by new-onset hypertension with proteinuria presenting after 20 weeks of gestation, and depending on mild or severe forms may initially present with severe headache, visual disturbances, and hyperreflexia. "As arteries from these women exhibited increased expression of KCNQ3 we speculate the up-regulation of KCNQ3 in preeclampsia may lead to activation of those channels, thus enhancing their function following significant relaxation of ICA-204352 on CPA vessels in preeclampsia." (PMID 29579054, 2018).
pulmonary edema (1 paper, 2024). Accumulation of fluid in the lung tissues causing disturbance of the gas exchange that may lead to respiratory failure. "KCNC3, KCNQ3, and KCNMA1 are voltage-gated potassium ion channel proteins, and the downregulation of KCNC3 and KCNQ3 in yak lungs suggested that the expression of voltage-gated potassium ion channels decreases in yaks with age, reducing membrane depolarization and harmful effects of pulmonary edema." (PMID 38779034, 2024).
self-limited familial infantile epilepsy (1 paper, 2024). This syndrome is characterized by the onset of seizures between 3 and 20 months of age (peak 6 months). "To date, there are three KCNQ3-related disorders: self-limited familial neonatal epilepsy (SLFNE); self-limited familial infantile epilepsy (SLFIE); and KCNQ3-related neurodevelopmental disorder (NDD)." (PMID 39062689, 2024).
speech disorder (1 paper, 2022). A term referring to disorders characterized by the disruption of normal speech. "The most prevalent symptoms of affected individuals who harbored KCNQ3 mutation were ID (95.5%), DD (87%), speech disorder (70.9%), behavioral abnormality (58%), seizures (54.8%), strabismus (45.1%), hypotonia (35.5%), and gait disturbance (22.6%)." (PMID 37543906, 2022).
status epilepticus (1 paper, 2021). Status epilepticus is defined as a continuous seizure lasting more than 30 min, or two or more seizures without full recovery of consciousness between any of them. "A recent study found GOF variants R230 and R227 in KCNQ3 that showed multifocal status epilepticus during sleep." (PMID 34093402, 2021).
neurodevelopmental disorder (8 papers, 2020 to 2026). A behavioral and cognitive disorder with onset during the developmental period that involves impaired or aberrant development of intellectual, motor, or social functions. "More recently KCNQ3 mutations are identified in patients with neurodevelopmental disorders and abnormal EEG." (PMID 38233770, 2024). "Moreover, GOF of KCNQ2 and KCNQ3 leads to neurodevelopmental disorders with no established treatments, while LOF (KCNQ2 and KCNQ3) causes neuronal hyperexcitability or neonatal seizures." (PMID 41155561, 2025).
tumor (7 papers, 2017 to 2025). "In PTC, KCNQ3 has emerged as a hub gene associated with lymph node metastasis and recurrence, with transcriptomic analyses revealing its robust upregulation in tumor tissues and cell lines, including B-CPAP and TPC-1, compared to normal thyroid epithelium." (PMID 41250218, 2025). "Specifically, high KCNQ3 expression was found to correlate strongly with gender, positive lymph node metastasis, and larger primary tumor size." (PMID 41250218, 2025). "IHC demonstrated markedly elevated KCNQ3 protein levels in tumor epithelium relative to adjacent follicular epithelial cells, with 28 of 45 tumors exhibiting moderate to strong staining versus 35 of 45 normal tissues exhibiting weak to moderate expression." (PMID 41250218, 2025). "In this study, we elucidate a novel oncogenic role for KCNQ3 in PTC, demonstrating its significant upregulation in tumor tissues and its association with poor prognosis." (PMID 41250218, 2025). "While historically studied in cardiac and neural contexts, emerging evidence implicates KCNQ family members in oncogenesis, notably in gastrointestinal malignancies, where KCNQ3 promotes epithelial-mesenchymal transition and tumor proliferation via Wnt signaling." (PMID 41250218, 2025). "We also find a weak but significant correlation between KCNQ1 and KCNQ3 expression and tumour stage in patient data, suggesting that this finding may be extended to human cancer." (PMID 37748809, 2023). "Notably, within single microscopic fields, KCNQ3 expression displayed a gradient, with intense staining in tumor cells, moderate staining in partially differentiated follicular cells, and minimal staining in normal thyroid epithelium, correlating with tumor progression." (PMID 41250218, 2025). "Our study provides compelling evidence that KCNQ3 is significantly upregulated in PTC tissues, driving tumor cell proliferation, migration, and progression through mechanisms independent of KCNQ2." (PMID 41250218, 2025). "GABA receptor signaling pathway enrichment was defined by elevated expression of GABRB3 and potassium channel genes, KCNN1, KCNN2, and KCNQ3, and decreased expression of ADCY2, which have all been indicated as important in tumor growth (32, –, 34)." (PMID 28049147, 2017). "KCNQ3 was upregulated in PTC and drove tumor cell proliferation and migration." (PMID 41250218, 2025).